DDX41 (DEAD-box helicase 41)
Diseases named in the same sentence as DDX41 in open-access papers (continued):
Sharing a sentence is not in itself a finding about the gene and the disease.
myeloid neoplasm (continued). "Interestingly, mutations in spliceosome proteins are frequently found in myeloid neoplasms, but they appear to be mutually exclusive with DDX41 mutations in MDS/AML patients." (PMID 39185415, 2024). "In the present review, we summarize the functions of DDX helicases in critical biological processes, particularly focusing on DDX41’s association with cellular molecules and the mechanisms underlying its roles in innate immunity, hematopoiesis and the development of myeloid malignancies." (PMID 39185415, 2024). "We strongly suspected that his AML was a myeloid neoplasm with a germline DDX41 mutation." (PMID 39526222, 2024). "However, further studies are clearly needed to fully elucidate the mechanisms by which DDX41 variants lead to myeloid neoplasms." (PMID 38203823, 2024). "Furthermore, germline predisposition genes exhibit age-related differences, with germline DDX41 variants observed in approximately 2.4–3.8% of patients with myeloid neoplasms and are prevalent in older age." (PMID 38137719, 2023). "Diseases reported to be associated with DDX41 mutations include myeloproliferative neoplasms, chronic lymphocytic leukemia, chronic myeloid leukemia, multiple myeloma, and Hodgkin and non-Hodgkin lymphomas other than myeloid neoplasms." (PMID 36672294, 2023). "In contrast, genes other than DDX41 are known to cause myeloid neoplasms in younger age groups, and there may be racial differences (for instance, between European and East Asian) in the distribution and frequency of genes that cause germline predisposition." (PMID 38137719, 2023). "The pathology of DDX41 mutations in myeloid neoplasms may be related to a disruption of the gene’s normal functions involving multiple functions in RNA biology." (PMID 36672294, 2023). "These ideas may explain why carriers of germline DDX41 variants generally develop myeloid malignancy at older ages." (PMID 36229594, 2022). "Beyond DDX41, mutations in genes that encode RNA splicing-related factors implicated in myeloid malignancies are observed in about 40–60% of MDS patients; of note, frequently mutated genes (namely, SF3B1, SRSF2 and U2AF1) all encode factors involved in the recognition of the 3’SS." (PMID 36119490, 2022). "In this cohort, DDX41 mutations were found only in 0.8% of patients with myeloid neoplasms." (PMID 35844724, 2021). "We speculate that these mutations or fusion genes may interact with germline DDX41 variants in the development of myeloid neoplasms." (PMID 35844724, 2021). "However, limited studies are describing the mutation profile of DDX41 other than myeloid neoplasms in hematological disease." (PMID 35844724, 2021). "This is consistent with the late age of onset of myeloid malignancy for DDX41 predisposition." (PMID 34387894, 2021). "It suggested that the pathogenesis of DDX41 mutations in ALL may differ from myeloid tumors, which merits further study." (PMID 35844724, 2021). "However, DDX41 mutations were present in 1.5% of patients with myeloid neoplasm in a cohort of 1,000 patients." (PMID 28955657, 2017). "For instance, elucidating the role of a previously uncharacterized germline DDX41 variant is of crucial importance to genetic counselling of an affected carrier as well as family risk relatives, given considerations of familial predisposition to myeloid malignancies." (PMID 37434984, 2023). "Clinically, DDX41-related myeloid neoplasms are characterized by late onset, male predominance, hypocellular marrow, and relatively favorable outcomes." (PMID 41303035, 2025). "Background/Objectives: DDX41, DEAD-box RNA helicase 41 gene located on chromosome 5q25.3, is one of the most mutated genes in patients with germline predisposition to myeloid neoplasms." (PMID 40407636, 2025). "The role of DDX41 in the pathogenesis of myeloid neoplasms has yet to be fully elucidated even though several studies were reported." (PMID 38514771, 2024).
myeloid neoplasm (continued). "Beyond its immune sensing functions, DDX41 has been identified as a tumor suppressor gene in myeloid neoplasms." (PMID 39185415, 2024). "Germline mutations in the DDX41 gene, telomere biology disorders, GATA2, and thrombocytopenia-associated disorders are associated with myeloid malignancies in older adults." (PMID 38137443, 2023). "In the context of tumorigenesis, mutations in DDX41 are associated with myeloid neoplasms myelodysplastic syndromes (MDS) and acute myeloid leukemia (AML), and excessive R-loops are found in DDX41 mutated cells." (PMID 37778731, 2023). "The germline mutations of DDX41, also known as DEAD box RNA helicase 41, have been found in about 1.5% of myeloid neoplasms (MNs)." (PMID 35246110, 2022). "We conclude that the vulnerability in DNA replication that partially remains in daughter cells would be essential to explain the unique phenotype of DDX41-related myeloid malignancies." (PMID 36229594, 2022). "In myeloid malignancies, patients with a ‘double-hit’ in a gene such as CEBPA, RUNX1, or DDX41 often have one variant in the germline with a VAF between 40 and 60%, and a second variant of somatic origin with variable VAF." (PMID 34298596, 2021). "Somatic DDX41 variants occurred throughout the whole coding region in ALL, but in the myeloid neoplasm, 80% of them were hotspot R525H." (PMID 35844724, 2021). "DDX41 mutations were identified in 0.8% of patients (six AML, one chronic myelomonocytic leukemia [CMML]) with myeloid neoplasm." (PMID 35844724, 2021). "The prognosis of myeloid neoplasms with DDX41 variants is not necessarily worse than for those without a known genetic background, regardless of the tendency to be categorized as high-risk." (PMID 38203823, 2024). "However, it is clear that DDX41’s interaction with cellular proteins also plays a role in its disease-modifying function in myeloid neoplasms." (PMID 39185415, 2024). "Moreover, deletions of chromosome 5q (del(5q)) involving the DDX41 locus have been detected in patients with myeloid neoplasms (MN)." (PMID 39185415, 2024). "First identified in 2015 as predisposing mutations for myeloid neoplasms by a study of an index family with a strong history of MDS/AML, a significant proportion of hereditary myeloid neoplasms were associated with the DDX41 mutations by affecting RNA biology and innate immunity." (PMID 36672294, 2023). "Notably, germline loss-of-function mutations in DDX41 and RUNX1 cause myeloid neoplasm predisposition." (PMID 36814285, 2023). "This suggests that a 50% reduction of DDX41 expression or function affects hematopoiesis to some degree, but that this level does not impair the enzyme sufficiently to cause myeloid malignancies." (PMID 36119490, 2022). "Somatic GATA2 mutations rarely occur in GDMM (i.e., biallelic) unlike for germline RUNX1, CEBPA, and DDX41‐driven myeloid malignancies where biallelic mutations are common." (PMID 34387894, 2021). "DDX41 may play a role in the pathogenesis of myeloid neoplasms with del(5q), since some of these deletions include DDX41 locus, leading to haploinsufficiency." (PMID 28955657, 2017). "This discrepancy may be attributed to the distinct molecular mechanisms underlying MDS and AML, DDX41 mutations may play a more prominent role in the early stages of myeloid malignancies, such as MDS, rather than in the more genetically complex AML." (PMID 40257479, 2025). "Although DDX41 has an established predisposition to myeloid malignancies, ILD has not been previously appreciated, and a larger patient cohort will be needed to establish whether there is an associated risk." (PMID 36853803, 2023).
myeloid neoplasm (continued). "The prevalence of DDX41 germline mutations is not known; however in a study screening 1000 myeloid neoplasm cases, DDX41 were identified in 1.5%, half of which were germline, suggesting that identification of a DDX41 mutation should prompt consideration of germline analysis." (PMID 27248996, 2016). "All patients found to have an HHMS were diagnosed with a myeloid neoplasm under age 50, except for the patients with RUNX1 and DDX41 PVs, who were diagnosed in their 60s." (PMID 40936482, 2025). "Although the DDX41 gene is characterized by the development of familial myeloid neoplasms, the mean age of onset is 60 years, which is no different from that of unmutated myelodysplastic syndrome (MDS) and AML." (PMID 39526222, 2024). "In patients with myeloid neoplasms and germline predisposition without potential organ dysfunction (i.e., patients with germline mutation in RUNX1, DDX41, CEBPA and so on), no specific complication after HSCT has been reported till date." (PMID 36185231, 2022).
myelodysplastic syndrome (37 papers, 2017 to 2026). A clonal hematopoietic disorder characterized by dysplasia and ineffective hematopoiesis in one or more of the hematopoietic cell lines. "The DDX41 gene encoding the DEAD-box RNA helicase 41 protein (DDX41) is subject to extensive germline genetic variation, and certain variants create a predisposition to develop myelodysplastic syndrome and acute myeloid leukemia." (PMID 40747827, 2025). "DDX41 variants are currently known to represent the most common germline alterations in adult myelodysplastic syndromes, accounting for 0.5–4% of all acute myeloid leukemia or myelodysplastic syndrome cases in adults." (PMID 37696923, 2023). "Among these genes, recent literature shows an association between germline DEAD-Box Helicase 41 (DDX41) mutations and familial MN, including myelodysplastic syndromes (MDS)." (PMID 36923434, 2023). "Dead box helicase 41 (DDX41) was also associated with the development of genomic instability and immune abnormalities during myelodysplastic syndrome and acute myeloid leukemia." (PMID 37903125, 2023). "Families with DDX41 mutations display an autosomal dominant inheritance, with a clinical picture dominated by late onset of either myelodysplastic syndrome (MDS) or acute myeloid leukemia (AML)." (PMID 35246110, 2022). "DDX41 is involved in pre-mRNA splicing and has tumour suppressor activity, with mutations in DDX41 being associated with Myelodysplastic syndromes (MDS)." (PMID 35769258, 2022). "Mutations in DDX41 are associated with myelodysplastic syndromes (MDS), acute myeloid leukemia (AML), and myeloid neoplasms (MNs)." (PMID 36761420, 2022). "Furthermore, the helicase DDX41 scaffolds METTL14-METTL3-YTHDC1 interactions to promote R-loop removal, a process disrupted in myelodysplastic syndromes due to DDX41 deficiency." (PMID 40905498, 2025). "Moreover, the germline DDX41 mutation has been linked to both acute myeloid leukemia/myelodysplastic syndrome and B-cell lymphoma, further highlighting the complex genetic interactions involved." (PMID 39001408, 2024). "For instance, DDX41 variants identified in AML/myelodysplastic syndrome (MDS) panels at a variant allele frequency (VAF) greater than 40% are germline in 94% of patients." (PMID 40759574, 2025). "DEAD box helicase 41 (DDX41) mutations are the most prevalent predisposition to familial myelodysplastic syndrome (MDS)." (PMID 38514771, 2024). "Loss of function DDX41 variants have been associated with adult myelodysplastic syndrome (MDS) and/or acute myeloid leukemia (AML)." (PMID 39453476, 2024). "In myelodysplastic syndrome (MDS) with a Ddx41 mutation, the most frequent germline mutation is a frameshift mutation with aspartic acid (D) 52 or D140, resulting in an inactive Ddx41 protein and dysfunction." (PMID 38993792, 2024). "For instance, germline CEBPA and DDX41 mutations are related to the family predisposition to myelodysplastic syndrome (MDS) and AML." (PMID 35279121, 2022). "An increasing number of both inherited and acquired mutations in DDX41 gene are identified from myelodysplastic syndrome and/or acute myeloid leukemia (MDS/AML) patients." (PMID 27502187, 2017). "In addition to its roles in innate immunity, mutations in the DEAD domain of human DDX41 are associated with myelodysplastic syndrome (MDS) and acute myeloid leukemia (AML)." (PMID 39158380, 2025). "DDX41 is a conserved DEAD-box RNA helicase affecting RNA splicing and found to be associated with the myelodysplastic syndrome and innate immunity." (PMID 41404809, 2025).
myelodysplastic syndrome (continued). "Mutations in DDX41 have been linked to an increased percentage of blasts and a higher risk of developing acute myeloid leukemia (AML) in individuals with myelodysplastic syndrome with excess blasts." (PMID 38785456, 2024). "DDX41 is also a tumor suppressor in familial and sporadic myelodysplastic syndrome/acute myelogenous leukemia (MDS/AML)." (PMID 39185415, 2024). "Observations of inherited variants in DDX41, a DEAD box RNA helicase gene, causing susceptibility to myelodysplastic syndrome and myeloid leukemias, offer additional proof of the important regulatory roles of ribosome biosynthesis and RNA processing in cancer." (PMID 37696923, 2023). "Inherited DDX41 mutations cause familial predisposition to hematologic malignancies including acute myeloid leukemia (AML) and myelodysplastic syndromes (MDS), with the majority of DDX41 mutated MDS/AMLs described to date harboring germline DDX41 and co-occurring somatic DDX41 variants." (PMID 37434984, 2023). "Germline mutations of DDX41 promote the development of myelodysplastic syndromes (MDS) with age, and germline mutations predispose individuals to somatic secondary mutation of DDX41 in the healthy allele which is strongly associated with the development of secondary AML." (PMID 34680866, 2021). "DDX41 is one of the most frequently altered genes in familial acute myeloid leukemia/myelodysplastic syndrome (AML/MDS)." (PMID 40257479, 2025). "The discovery in 2015 that DDX41 mutations are found in acute myeloid leukemia (AML) and myelodysplastic syndromes (MDS) is relevant to this revision." (PMID 36119490, 2022). "Using zebrafish, we showed that DEAD-box helicase 41 (DDX41), a factor mutated in inherited adult-onset myelodysplastic syndrome (MDS), suppresses R-loop accumulation." (PMID 34868827, 2021). "Familial and sporadic mutations in human DDX41 lead to acute myeloblastic leukemia and myelodysplastic syndromes (AML/MDS), suggesting that it also functions as a tumor suppressor." (PMID 29871919, 2018). "DDX41 was recently identified as a tumor suppressor gene in familial and sporadic myelodysplastic syndrome/acute myeloid leukemia (MDS/AML), as well as other hematological malignancies." (PMID 29871919, 2018). "Of special note, DDX41 plays a significant role in myeloid malignancies, including acute myeloid leukemia (AML) and myelodysplastic syndromes (MDS)." (PMID 38139802, 2023).
acute myeloid leukemia (32 papers, 2016 to 2026). Acute myeloid leukemia (AML) is a group of neoplasms arising from precursor cells committed to the myeloid cell-line differentiation. "Constitutional pathogenic variants in DDX41 predispose to myelodysplasia and acute myeloid leukaemia." (PMID 41873058, 2026). "For example, while germline DDX41 mutations are inherited in an autosomal dominant fashion, only 25–50% of DDX41 carriers develop DDX41-associated acute myeloid leukemia at a median age of onset of 71 years." (PMID 41457124, 2025). "Mutations in another RNA helicase, the DEAD-box protein DDX41, have been identified in familial and acquired cases of myelodysplasia and acute myeloid leukemia, and these mutations in DDX41 also give rise to defects in pre-mRNA splicing." (PMID 35768279, 2022). "Germline loss-of-function mutations in DDX41 lead to predisposition to acute myeloid leukemia in adulthood." (PMID 34916496, 2021). "Mutations and dysregulation of DDX41 have been reported to be associated with familial myelodysplasia syndrome (MDS)/acute myeloid leukemia (AML)." (PMID 39246323, 2024). "Germline heterozygous variants in DDX41 have been reported in familial myelodysplasia syndrome (MDS)/acute myeloid leukemia (AML) patients; most patients also acquired a somatic variant in the second DDX41 allele." (PMID 39453476, 2024). "Myeloid neoplasm with the germline DDX41 mutation has been recognized as a cause of MDS in adults, with hematological features that include leukopenia and erythroid dysplasia with hypocellular bone marrow with increased blast counts and acute myeloid leukemia." (PMID 38785456, 2024). "Deleterious germline DDX41 variants are the leading cause of heritable predisposition to myelodysplastic neoplasia and acute myeloid leukemia (MDS/AML)." (PMID 41703027, 2026). "In hematological malignancies, such as acute myeloid leukemia (AML) and myelodysplastic syndrome, the loss or mutation of the DEAD-box helicase DDX41, an R-loop resolving helicase, leads to the accumulation of R-loops." (PMID 40629041, 2025). "A recent report suggested that if patients with DDX41 germline mutation with acute myeloid leukemia (AML) do not receive allogeneic HSCT at first complete remission (1CR), most of them would eventually relapse." (PMID 39526222, 2024). "For hematological malignancies, hereditary predisposition was first identified in chronic lymphocytic leukemia (CLL) and acute myeloid leukemia (AML), which has led to the identification of several germline mutations, such as RUNX1, CEBPA, GATA2, ANKRD26, DDX41 and ETV6 mutations." (PMID 36998465, 2023).